Y_RNA (Y RNA )
Gene: Miscellaneous RNA gene on chromosome 11 (10,725,903 to 10,726,004, forward strand). Ensembl gene ENSG00000206858.
Homologues: Orthologues: chimpanzee Y_RNA (98% identical), macaque Y_RNA (91% identical). Paralogues in human: Y_RNA (90% identical), Y_RNA (89% identical), Y_RNA (88% identical), RNY3 (87% identical), Y_RNA (87% identical), RNY3P1 (86% identical), Y_RNA (86% identical), Y_RNA (85% identical), RNY3P14 (84% identical), Y_RNA (84% identical), Y_RNA (83% identical), RNY3P11 (82% identical), and 94 more.